IL1B (interleukin 1 beta)
Diseases named in the same sentence as IL1B in open-access papers (continued):
Sharing a sentence is not in itself a finding about the gene and the disease.
delirium (49 papers, 2014 to 2026). A disorder characterized by confusion; inattentiveness; disorientation; illusions; hallucinations; agitation; and in some instances autonomic nervous system overactivity. "As a pro-inflammatory cytokine, IL-1b is highly associated with delirium development as well as having a part in the etiology of early delirium." (PMID 39700095, 2024). "The pro-inflammatory cytokines, IL-6, TNF-α, IL-1α, IL-1β, have been implicated in delirium-like behavioral changes, such as impaired concentration, diminished motivation, and psychomotor retardation in critically ill patients." (PMID 36030220, 2022). "Consistent with this idea, IL-1β levels have been associated with delirium in hip fracture patients and in septic encephalopathy." (PMID 29875474, 2019). "Elevated CSF levels of IL-1β have recently been shown to be associated with delirium in hip-fracture patients." (PMID 27633985, 2017). "Based on the association of neuroinflammation with delirium, the levels of IL-1β, IL-8 and TNF-α in CSF were measured before and after WAY-100635 treatment." (PMID 27760517, 2016). "In their prospective cohort study they found significant associations between STNFR1, STNFR2, IL-1β and adiponectin concentrations and the development of delirium." (PMID 25042374, 2014). "In this study we demonstrate that elevated serum inflammatory markers STNFR1, STNFR2, adiponectin and IL-1β were associated with the occurrence of delirium in critically ill patients." (PMID 24886875, 2014). "We furthermore found that elevated postoperative S100β, IL-6, and IL-1β concentrations are associated with an increased risk of developing delirium, and interventions reducing their perioperative release may decrease the risk for POD." (PMID 37373482, 2023). "TNF-α and IL-1β are two prototypical cytokines hardwired to NF-κB signaling and are implicated in the development of age-related postoperative complications including delirium and postoperative cognitive dysfunction." (PMID 27493629, 2016). "In addition, IL-1β interferes with cholinergic signal transduction, a major neurotransmitter implicated in the pathogenesis of delirium." (PMID 24886875, 2014). "We hypothesised that delirium would be associated with increases in the pro-inflammatory cytokines IL-1β and IFN-γ, and a marker of astrocytosis GFAP, and decreases in anti-inflammatory IGF-1 and IL-1ra, and that this would be shown in the CSF." (PMID 25124807, 2014). "STNFR1, STNFR2, adiponectin and IL-1β were associated with delirium." (PMID 24886875, 2014). "Interestingly, serum and cerebrospinal fluid concentration levels of IL-1b are elevated in patients with delirium, which may explain the association demonstrated in this study between delirium and sarcopenia in the acute setting." (PMID 39012665, 2024). "With the exception of IL-1β and IL-12 all inflammatory biomarkers could be linked to delirium." (PMID 31263968, 2019). "They found higher concentrations of Ng and interleukin-1 beta in the delirium group on the day of intensive care unit admission, and at delirium diagnosis, compared with the control group." (PMID 41218946, 2025). "Peripheral inflammation is a well-established trigger of delirium, and IL-1, IL-1β, IL-6, IL-8, tumor necrosis factor (TNF), and prostaglandin E2 (PGE2) stimuli trigger tissue macrophage and blood monocyte activation and secretion of inflammatory mediators." (PMID 41459337, 2025). "Among the unique proteins, we focused on the top 13 most investigated proteins (IL-6, CRP, IL-8, S100B, IL-10, TNF-a, IL-1b, Cortisol, MCP-1, GFAP, IGF-1, IL-1ra, and NFL) that are significantly associated with delirium." (PMID 39700095, 2024). "Inflammatory mediators such as IL-1B, IL-6, IL-8, IL-10, TNF-alpha, and C-reactive protein (CRP), have all shown associations with delirium." (PMID 36803215, 2023).
delirium (continued). "This study evaluated the effect of nine genetically predicted inflammatory factors (TNF-α, CPR, IL-1α, IL-1β, IL-2, IL-6, sIL-6Rα, Soluble gp130, and IL-8) on delirium." (PMID 37649721, 2023). "There is an increased systemic production of interleukin-1 α (IL-1α), IL-1β, IL-6, IL-10, and tumor necrosis factor α (TNF-α), which are implicated in the pathogenesis of delirium." (PMID 36030220, 2022). "A recent systematic review has shown that IL-1β, IL-6, IL-8, IL-10, and IFN-γ are significantly associated with delirium onset, displaying higher levels, both in plasma and CSF, in relation to baseline." (PMID 34736422, 2021). "After correction for monocyte count, patients with delirium had reduced LPS-induced TNFα, IP-10, IL-1β, IL-6, and IL-12 release." (PMID 29669581, 2018). "In order to investigate the possible connection of WAY-100635 with inflammatory pathways in the occurrence of delirium, a key pro-inflammatory cytokine IL-1β in CSF was analyzed before and after WAY-100635 treatment." (PMID 27760517, 2016). "The finding of elevated IL-1β in the CNS in delirium has biologically plausible implications in terms of the role of IL-1β in sickness behaviour, memory and neuroinflammation, and potential consequences in terms of neurotoxicity if this response is sustained." (PMID 25124807, 2014). "Ritter and colleagues studied TNFα, soluble TNF receptor (STNFR)-1, STNFR2, IL-1β, IL-6, IL-10 and adiponectin in systemic inflamed patients in relation to delirium." (PMID 25042374, 2014). "Out of all analyzed biomarkers, only STNFR1 (P = 0.003), STNFR2 (P = 0.005), adiponectin (P = 0.005) and IL-1β (P < 0.001) levels were higher in delirium patients." (PMID 24886875, 2014). "Using all values including those extrapolated from the standard curve, CSF IL-1β was higher in the group with delirium at any stage (median 1.02 pg/ml; IQR 0.66–1.74) compared to the no delirium group (median 0.66 pg/ml; IQR 0–1.02) (Mann Whitney U p = 0.02)." (PMID 25124807, 2014). "In this study, IL-1ra was higher only in patients with active delirium suggesting that this was after a rise in IL-1β, however in clinical terms, a 30 minute delay is unlikely to be relevant." (PMID 25124807, 2014). "We found elevated CSF IL-1β in those with incident delirium, that is, those who were about to develop delirium, often in the immediate post-operative period." (PMID 25124807, 2014). "This study provides novel evidence of CNS inflammation involving the IL-1β family in delirium and suggests a rise in CSF IL-1β early in delirium pathogenesis." (PMID 25124807, 2014). "This protective effect may be associated with the observed sustained downregulation of the peripheral NLRP3/caspase-1/IL-1β signaling pathway, which consequently weakens the link between early postoperative inflammation and delirium." (PMID 41998765, 2026). "IL-1β has emerged as an essential mediator in delirium pathophysiology." (PMID 41375722, 2025). "In patients with delirium, it was demonstrated that pro-inflammatory cytokines, such as IL-6, IL-1α, IL-1β, and TNF-α, are associated with delirium-like behavioral disturbances, such as diminished concentration, altered motivation, and decreased psychomotor activities." (PMID 41156174, 2025). "Furthermore, several studies have examined the potential role of IL-1α, IL-1β, IL-2, and IL-8 in the development of delirium." (PMID 37649721, 2023). "The results of this MR analysis did not support that peripheral TNF-α, CRP, IL-1α, IL-1β, IL-2, IL-6, sIL-6Rα, soluble gp130, and IL-8 were causally associated with delirium." (PMID 37649721, 2023). "The literature concludes that no specific biomarkers afford complete certainty in the early diagnosis of delirium, though it has been postulated that all inflammatory biomarkers could be related to delirium, with the exception of IL-1β and IL-12." (PMID 36013306, 2022).
delirium (continued). "Furthermore, previous researchers indicated that cholinergic system and inflammation are common pathways involved in delirium pathophysiology and incriminated IL-1β as the major inflammatory factor." (PMID 27760517, 2016). "In conclusion, this study supports the hypothesis that there are inflammatory mechanisms in delirium, and for the first time suggests a role for CNS IL-1β in the delirium pathogenesis cascade." (PMID 25124807, 2014). "IL-1β was increased in CSF in patients about to develop delirium, indicating that CNS IL-1β production may be an early event in delirium pathogenesis." (PMID 25124807, 2014). "Animal studies modelling delirium or acute cognitive dysfunction induced by systemic inflammation in aged rodents or those with prior neurodegeneration have consistently shown exaggerated CNS IL-1β responses to equivalent systemic stimulation." (PMID 25124807, 2014). "This may be because significant generation or release of CNS IL-1β is an early phenomenon in delirium pathogenesis." (PMID 25124807, 2014). "For example, a systematic evaluation of animal experiments has shown that microglia activation is associated with elevated levels of IL-1β, TNF-α, and Toll-like receptors (activated microglia release cytokines and chemokines, such as IL-1β, IL-6, and TNF-α), and may lead to delirium." (PMID 40661144, 2025). "Similarly, researchers found that IL-1β levels were higher in delirium patients." (PMID 41459337, 2025). "LM‐ and AS‐induced delirium led to microglial activation in the hippocampus as evidenced by up‐regulation of microglial activation‐related genes (such as Il6ra, Tyrobp, Cd68, Aif1, Csf1r, and Trem2) and of relevant inflammatory factors (such as Il‐1β, Tnfα, Ccl2, Ccl5, and Ccl8)." (PMID 35713240, 2022). "Studies in older adults with delirium after hip fracture repair confirmed the presence of high levels of IL-1β in cerebrospinal fluid (CSF), suggesting that IL-1 may represent a valuable biomarker for identifying and possibly treating patients at risk for PNDs." (PMID 35603196, 2022). "Moreover, for those patients where both serum and CSF analyses were possible, we calculated CSF:serum ratios for IL-1β and found that this ratio was higher in the delirium group (delirium group N = 7, median ratio 1 (IQR 0.18–1.27), no delirium group N = 7, ratio 0 (0–0.48), MWU p = 0.02)." (PMID 25124807, 2014). "Inflammatory markers such as interleukin-1B (IL-1B), interleukin-6 (IL-6), and tumor necrosis factor-a (TNF-a) have been observed to be elevated in patients with delirium." (PMID 38263028, 2024). "We measured the expression of COX-2, IL-1β, IL-6, and TNF-α in the blood using ELISA on both the day of delirium onset (D1) and the 5th day after delirium onset (D5)." (PMID 38902693, 2024). "We have summarized the 13 most studied proteins (IL-6, CRP, IL-8, S100B, IL-10, TNF-a, IL-1b, Cortisol, MCP-1, GFAP, IGF-1, IL-1ra and NFL) about delirium." (PMID 39700095, 2024). "The intra-hippocampus and intra-BLA injections of WAY-100635 improved the delirium-like behavior of rats by significantly reducing the expression of NLRP3 inflammasome and the release of IL1-β and IL8 into CSF." (PMID 27760517, 2016). "Elevated levels of pro-inflammatory cytokines, including IL-1β, IL-6, and TNF-α, have been consistently documented in the serum and cerebrospinal fluid of patients experiencing delirium, with meta-analyses showing 2–4-fold increases compared to non-delirious patients." (PMID 41375722, 2025). "Additionally, common cytokine imbalances in AID patients, especially the elevation of pro-inflammatory factors such as IL-1β, IL-6, TNF-α, have been found to be closely related to the occurrence of delirium." (PMID 40740958, 2025). "A systematic review of animal experiments indicated that activation of microglial was concerned with the elevated levels of IL-1β, TNF-α, and Toll-like receptors, and could contribute to delirium." (PMID 36455873, 2022).
delirium (continued). "The results of this study showed that the levels of preoperative cerebrospinal fluid IL-1β and TNF-α were higher in delirium than in non-delirium patients, suggesting that patients with high levels of preoperative neuroinflammation are prone to delirium postoperatively." (PMID 35294925, 2022). "Compared to patients without delirium, delirious patients exhibited reduced release of TNFα, IP-10, IL-1β, IL-6, and IL-12 after whole blood stimulation with LPS." (PMID 29669581, 2018). "The authors found that CSF IL-1β was significantly higher in patients with new-onset delirium compared to patients without delirium and that CSF to serum IL-1β ratios were higher in delirious than non-delirious patients." (PMID 27577265, 2016). "CSF IL-1β was higher in patients with incident delirium compared to never delirium (incident delirium 1.74 pg/ml (1.02–1.74) vs. prevalent 0.84 pg/ml (0.49–1.57) vs. never 0.66 pg/ml (0–1.02), Kruskal–Wallis p = 0.03)." (PMID 25124807, 2014). "Indeed, increased levels of cerebrospinal fluid and IL-1B and IL-8 were reported in patients with hip fracture and delirium compared to patients who did not have delirium." (PMID 39860413, 2025). "Having some contradictory findings, IL-1b could not be served as a potential individual biomarker for delirium." (PMID 39700095, 2024). "In summary, the MR analysis indicated that there may not be a causal association between delirium and the following factors: TNF-α, CRP, IL-1α, IL-1β, IL-2, IL-6, sIL-6Rα, soluble gp130, and IL-8." (PMID 37649721, 2023). "Chi-squared analysis of whether or not IL-1β was detected in CSF revealed that if detected, it was more likely to come from a patient in the delirium group (Pearson chi-squared 3.79 p = 0.05)." (PMID 25124807, 2014). "Subgroup analysis revealed that CSF IL-1β was higher in patients with incident delirium (median 1.74 pg/ml; IQR 1.02–1.74) compared to prevalent delirium (0.84 pg/ml; 0.49–1.57) and those who never developed delirium (0.66 pg/ml; 0–1.02) (Kruskal–Wallis p = 0.03)." (PMID 25124807, 2014). "Furthermore, the increased CSF:serum IL-1β ratios in delirium versus no delirium offer tentative support for the microglial priming hypothesis that systemic inflammation produces exaggerated CNS inflammatory responses in those with prior CNS pathology and that this may have a role in delirium." (PMID 25124807, 2014).
sarcopenia (49 papers, 2017 to 2026). Progressive decline in muscle mass due to aging which results in decreased functional capacity of muscles. "Systemic inflammatory markers such as C-reactive protein (CRP) and interleukin-1β (IL-1β) are elevated in individuals with sarcopenia, indicating a strong association between inflammation and muscle loss." (PMID 40943447, 2025). "Studies also associate elevated IL-1β levels with sarcopenia, highlighting its role in mediating inflammatory responses and influencing cellular proliferation, differentiation, and apoptosis, primarily orchestrated by macrophages." (PMID 40429815, 2025). "A recent systematic review and meta-analysis on geriatric diseases also supports this, highlighting elevated TNF-α and IL-1β levels as being associated with sarcopenia and frailty." (PMID 39847510, 2025). "Bioinformatics analysis identified 78 biphenotypic target genes shared by LT and sarcopenia, with hub genes including IL1B, ADIPOQ, and TNF showing strong associations." (PMID 41211064, 2025). "IL-1b within 48hours of admission/surgery was positively associated with sarcopenia status at 7days (β 0.24, CI 0.06-0.42)." (PMID 39012665, 2024). "The level of circulating pro-inflammatory cytokines (interleukin (IL)-6, tumor necrosis factor (TNF) or IL-1β) is a risk factor in cardiovascular and neurodegenerative diseases and is also associated with sarcopenia and frailties." (PMID 38495887, 2024). "IL-1b measured within 48 hours of admission/surgery was positively associated with sarcopenia status at 7 days (β 0.24, CI 0.06 - 0.42), and resistin was negatively associated (β -0.12, CI -0.23 - -0.01)." (PMID 39012665, 2024). "No systemic biomarkers were consistently associated with both sarcopenia status at 7 days and changes in muscle quantity and quality at 7 days post-admission/surgery, although IL-1b was positively associated with sarcopenia status." (PMID 39012665, 2024). "The ROC analysis of cfDNA, CRP, IL-1β and bilirubin ranged from 0.6 to 0.7, which confirms the association between sarcopenia and inflammatory mediators and indicates high clinical usefulness of cfDNA and bilirubin in sarcopenia prediction." (PMID 37465171, 2023). "There is growing evidence that increasing pro-inflammatory markers such as TNF-α, IL-1β, IL-6 are the main cause of skeletal muscle wasting and sarcopenia." (PMID 34041251, 2021). "Either inflammatory cytokines, including TNF and IL-1β, or anti-inflammatory cytokines such as IL-10 have been implicated in sarcopenia-related frailty in humans and rodents." (PMID 33918334, 2021). "Inflammation due to increased generation of cytokines such as TNFα, IL-1β and IL-6 has been implicated in the pathogenesis of sarcopenia." (PMID 33260150, 2020). "However, there was a positive association between IL-1b serum concentrations and sarcopenia status at 7 days." (PMID 39012665, 2024). "Active IL-1β has been associated with increased likelihood of all-cause mortality, and both IL-1 and IL-18 participate in the inflammatory aging process and in sarcopenia." (PMID 36499366, 2022). "The analysis of E-DII with cfDNA (Classifier Accuracy 79.7%, p = 0.001) showed a higher diagnostic utility in sarcopenia prediction then conventional inflammatory markers such as IL-1β, IL-6 and TNFα, which may have important implications in defining healthy or unhealthy ageing." (PMID 41345186, 2025). "The analysis of classifier accuracy for E-DII + cfDNA showed its higher diagnostic utility in predicting sarcopenia then conventional inflammatory markers such as IL-1β, IL-6 and TNFα, which may have important implications in defining healthy or unhealthy ageing." (PMID 41345186, 2025). "Systemic inflammation—driven by cytokines such as TNF-α, IL-1β, and IL-6—is known to promote muscle catabolism and intramuscular lipid accumulation, thereby contributing to both sarcopenia and myosteatosis." (PMID 41567660, 2025).